IL2 (interleukin 2)
Diseases named in the same sentence as IL2 in open-access papers (continued):
Sharing a sentence is not in itself a finding about the gene and the disease.
Immunodeficiency (continued). "Ginger polysaccharide has been shown to enhance cytokines IL-2, IL-4, TNF-α, and immunoglobulin Ig-G secretion in the serum of mice, thereby ameliorating immune deficiency." (PMID 38540831, 2024). "This differential dependency of Tregs and Tconvs on TCR signaling supports the beneficial effect of IL-2 administration plus calcineurin inhibition in diverse immune diseases." (PMID 38665907, 2024). "These EDCs disrupt the normal functioning of hormones in males and elevate the levels of pro-inflammatory cytokines such as IL-1b, IL-2, IL-6, IL-10, and IL-17A, leading to immune system disorders." (PMID 39636940, 2024). "This action of IL-2 signaling is extremely detrimental in patients with immune disorders characterized by high levels of Th cells such as Th2." (PMID 38711497, 2024). "There would be an immunodeficiency duringchildhood, resulting in a diminished pro-inflammatory response with lower levelsof pro-inflammatory cytokines such as IL-2." (PMID 37610949, 2023). "NK cells play a vital role in anti-cancer and anti-immune diseases, and AR can promote the production of IL-2 and enhance the activity of NK cells, although its direct effects on NK cells themselves have yet to be fully investigated." (PMID 37089929, 2023). "For that matter, IL-2 and IL-15 supplementation have been proposed as to improve the immune disorder and reduce mortality." (PMID 36238287, 2022). "IL-2 is also widely used to treat immunodeficiency diseases, but the complications of impaired renal function often occur during treatment." (PMID 35971094, 2022). "IL2RB-deficient patients show dysregulated IL2 and IL15 signaling, enhanced natural killer cell levels, and subsequent immunodeficiency and impaired antiviral immunity." (PMID 33633136, 2021). "Jak3 knockout mouse model showing Il-2, Il-4, Il-7, Il-9, and Il-15 conduction defects, elevated levels of Il-6 and Il-17a and severe immunodeficiency, defects in barrier function lead to Ulcerative colitis (UC)." (PMID 33777833, 2021). "As typical cytokines of Th1 lineage, IL-2 and IFN-γ have been implicated in the pathogenesis of multiple immune diseases." (PMID 31864413, 2019). "miR-31-5p was found to be underexpressed in T cells of patients with SLE; this molecule promotes the inhibition of the target gene RhoA and the downregulation of IL-2 expression and thus participates in immune disorders of SLE." (PMID 30836987, 2019). "PSG-1 has been shown to relieve immune dysfunction through the upregulation of serum IL-2, which increases lymphocyte proliferation and subsequently, longevity." (PMID 29344411, 2017). "IL-2Rα expression increases the affinity ofIL-2 binding ~100 times, facilitating IL-2 responses at low physiologicalconcentrations of IL-2.Compromised expression of IL-2 or IL-2Rα leads to the development of autoimmunediseases and immunodeficiency." (PMID 27936140, 2016). "The other approach with a goal to improve low-dose IL-2 therapy (3 × 105 IU/day) in immune disorders is based on its combination with glucocorticoids in an animal model of GVHD." (PMID 25322151, 2014). "Both immune deficiencies and autoimmune manifestations have been reported in ICL, which appears consistent with an impairment of both IL-7 and IL-2 systems." (PMID 23383227, 2013). "In this regard, it is especially disappointing that IL-2 administration had no discernible effect, given the numerous studies, noted previously, that point to a defect in IL-2 production as one of the hallmarks of the immunodeficiency of chronic HIV infection." (PMID 17260026, 2007). "Dogs could also be used to study novel therapeutic strategies for immunodeficiencies, such as IL-2 administration, which has been proposed for humans with CARMIL2 deficiencies." (PMID 38535207, 2024). "The results showed that the sodium hyaluronate health drink could improve thymus atrophy, repair spleen cell damage, promote the release of IL-2, IL-6 and TNF-α in serum, restore immune deficiency, and enhance immune function." (PMID 38540831, 2024).
Immunodeficiency (continued). "The increases in the proinflammatory cytokines IL-1a, IL-8, IL-17A, IL-12p40, TNF-β, MCP-1, IL-2, and IL-12p70 and the anti-inflammatory cytokines IL-10 and IL-13 observed in AD patients in our study are consistent with prior evidence of immune dysfunction in AD." (PMID 39346576, 2024). "In addition, serum inflammatory cytokines IL-1β and IL-2 were increased in the model groups compared to that of the immunodeficiency group." (PMID 37317157, 2023). "Therefore, modulation of IL-2/IL-2R and IL-7/IL-7R signaling with biological therapies has great potential as countermeasures to restore immune dysfunction of crew members." (PMID 37624890, 2023). "An interesting therapeutic implication is that Treg activation may be achievable in a relatively tissue antigen-agnostic manner with attenuated IL-2 muteins, which could be used in a broad spectrum of auto-immune diseases." (PMID 37809101, 2023). "This is in accordance with previous reports in that the expression levels of the IL-2 and IFN-γ genes are associated with AFB1-induced immune disorder, probably due to AFB1 poisoning causing DNA transcription and mRNA translation in lymphocytes and ultimately affecting protein biosynthesis." (PMID 36139027, 2022). "We hypothesized that feeding egg-PC will attenuate obesity-related immune dysfunction by increasing IL-2 production after T-cell stimulation." (PMID 35187037, 2022). "IL-2 is currently being used to treat auto-immune disorders and various cancers." (PMID 34071880, 2021). "For critical patients with COVID-19 pneumonia, appropriate IL-2 supplementation could be beneficial by improving the immune disorder so as to reduce mortality." (PMID 32513989, 2020). "In recent years, IL-2 was shown to have therapeutic efficacy by expanding distinct T cell compartments, since low-dose IL-2 preferentially expands Tregs versus other immune cells, and some Treg-biased anti-IL-2 antibodies (IL-2Ab) have been developed as therapies for immune diseases." (PMID 32795376, 2020). "The Rag2/IL2 gene mutation did not affect the normal physiological behavior of mice, but the mutated mice displayed the typical characteristics of immunodeficiency." (PMID 31134127, 2019). "Many studies have shown that the decrease of IL-2 can lead to cellular immune dysfunction." (PMID 30983991, 2019). "It is speculated that high levels of circulating oligosaccharides (in addition to intracellular accumulation) may contribute to the immunodeficiency seen in AM patients, since they bind to interleukin-2 (IL-2) receptors, disturbing IL-2-dependent responses." (PMID 29846843, 2018). "BCG vaccine reactivation has an important effect on the prognosis of combined immunodeficiencies, but this vaccine also helps to identify interferon gamma/interleukin 2 axis defects with BCG-itis and to determine T-lymphocyte function with a positive tuberculin (purified protein derivative) test." (PMID 28404538, 2017). "It is unclear whether the immunodeficiency in patients observed in our study results solely from the production of anti-IFN-γ antibodies or it is worsening by the reduction of IL-2 and TNF-α production." (PMID 25329064, 2014). "The development of most immune diseases depends on the cytokines interleukin-2 and interferon-γ produced by type 1 helper T cells (Th1), whereas the development of allergic diseases requires IL-4 and IL-5, both of which are produced by type 2 helper T cells (Th2)." (PMID 15710045, 2005). "Low-dose IL-2 can stimulate the proliferation of Treg cells in the peripheral blood of patients with D2T RA, shift the balance of effector T cells/Treg cells toward Treg cells, restore immune tolerance to a certain extent, and become a new means to improve the immune disorder of RA." (PMID 39981233, 2025). "Another study demonstrated a reduction in activation of CD4 cells, proinflammatory cytokine production IL-2, prevention of CD4/CD8 derangement and lymphocyte directed immune dysfunction." (PMID 40336073, 2025).
Immunodeficiency (continued). "Cytokine profiling showed decreased levels of IL-2, IL-6, IL-10, TNF-α, and IFN-γ, indicating broad-spectrum immune dysfunction." (PMID 40806124, 2025). "In patients with combined immunodeficiency, the CD4 lymphocyte response was characterized by both IFN-γ and IL-2 production." (PMID 38132279, 2023). "In patients with common variable immunodeficiency, there was a very poor number, if any, of S-specific CD4+ and CD8+ T cells expressing cytokines (IFN-γ, IL-2, and TNF-α)." (PMID 38132279, 2023). "Other specialist tests can help diagnosis in specific disorders such as dyskeratosis congenita (telomere length analysis), ectodermal dysplasia with immunodeficiency (response to TLRs), and X-SCID (response to IL-2 stimulation)." (PMID 33809703, 2021). "Cytokines affected by HHODC in this study, IL-2, IL-6, TNF-α, and IFN-γ, are documented as being among the many biomarkers affected by HIV-1 infection due to immune dysfunction." (PMID 29027985, 2017). "Further analysis of the relative importance of the presence of anti-IFN-γ antibodies and decreased IL-2 and TNF-α production in HIV-negative immunodeficiency with anti-interferon-γ antibodies and opportunistic intracellular microorganisms is warranted." (PMID 25329064, 2014). "Interleukin 2 (IL-2) was first considered to be an integral T-cell activator, yet, researchers found that mice lacking IL-2 or its receptor gene exhibited severe autoimmune symptoms instead of the expected immunodeficiency." (PMID 37275865, 2023). "We believe that when the immunodeficiency is aggravated, the body does not produce a strong immune response and enough cytokine, like interleukin-2 against Cryptococcus infection." (PMID 34625036, 2021). "However, subsequent studies showed that the dominant role of IL-2 is the maintenance of Treg cells, and not the development of effector and memory T cells, since loss of IL-2 signaling led to a break-down of immune tolerance and homeostasis rather than to immunodeficiency." (PMID 31920671, 2019). "Their reduced IL-2 produced by CD4 T cells, and their reduced TNF-α by both CD4 and CD8 cells may explain the immunodeficiency of such HIV− patients, in addition to the finding of autoantibodies to IFN-γ." (PMID 25329064, 2014). "Very recently, there were reported the results of the first clinical trials in patients with an immune disease, namely hepatitis C virus (HCV)-induced vasculitis, GVHD, or T1D, with a goal to induce Treg numbers and/or function with low-dose IL-2." (PMID 25322151, 2014). "We could not determine whether the immunodeficiency comes from an overall reduction in the production of IL2 by all lymphocytes or, alternatively, from a diminished fraction of IL2 producers within the particular T cell population." (PMID 40276114, 2025). "For instance, IL2 promotes the development of CD4+CD25+FoxP3+ Tregs, that represent an immunomodulatory T cell specialized subset able to neutralize the development of immune-mediated damage and to promote repair and regeneration of affected target-organs in systemic immune diseases." (PMID 33324641, 2020). "Here, we describe a human immunodeficiency-like condition characterized by a reduced frequency of CD3−C56dim cells with lower percentages of terminally differentiated NK cells, and accumulation of CD3−CD56bright cells in peripheral blood that exhibit altered activation in response to IL-2 and IL-15." (PMID 23240056, 2012). "Thus, it is possible that patients with LSM ≥25kPa had a lower production of IL-2, TNF-α, and IL-17A due to the taxing effect of bacterial translocation on the immune system, which may induce immune dysfunction and a lower production of key cytokines during severe cirrhosis." (PMID 30400258, 2018).
tuberculosis (97 papers, 2007 to 2026). A chronic, recurrent infection caused by the bacterium Mycobacterium tuberculosis. "Active tuberculosis is also associated with a decrease in polyfunctional and IL-2+ T cells and an increase in TNF-α+ CD4+ and CD8+ memory T cells." (PMID 39065554, 2024). "Interestingly, memory phenotype was not exclusively linked to the functional profile (except for IL-2-only cells which were mainly TCM) but was closely related to underlying tuberculosis stage." (PMID 23966657, 2013). "In the present study we evaluated the performances of IFN-γ and IL-2 based ELISPOT assays in children at risk for TB using an array of M. tuberculosis specific antigens." (PMID 23029377, 2012). "utilized machine learning techniques and found that among HIV-positive patients, those with tuberculosis exhibited significantly elevated levels of inflammatory markers including IL-2, IL-4, IL-6, IL-10, TNF-α, and IFN-γ." (PMID 41322408, 2025). "The considerable clinical experience with IL-2 has markedly enhanced its potential for advancing tuberculosis therapeutic agents and vaccine adjuvants." (PMID 38793728, 2024). "The panel we employed included cytokines that are elevated in tuberculosis, i.e., interferon gamma (IFNγ), IL-2, IL-5, IL-10, IL-17, GM-CSF and TNFα." (PMID 38415011, 2024). "This study aims to evaluate the diagnostic accuracy of a Mycobacterium tuberculosis (MTB)-specific triple-color FluoroSpot assay (IFN-γ/IL-2/TNF-α) in the differentiation of tuberculosis (TB) infection status in febrile patients." (PMID 39845975, 2024). "For example, IL-2 has been used to treat metastatic cancer and multi-drug-resistant tuberculosis, and shuffled IL-2 has also been shown to be an effective adjuvant to boost the immune response to the pasteurella multocida vaccine." (PMID 36290395, 2022). "In an effort to further enhance the protective immunity of rBCG strains against tuberculosis, IL-2 has been fused to Early Secreted Antigenic Target 6 (ESAT-6), a M. tuberculosis antigen absent in BCG." (PMID 35632582, 2022). "The existence of IL-2-producing T cells has been well correlated with effective treatment and the induction of long-term protection against tuberculosis." (PMID 32629975, 2020). "Recent publications also suggest that the accuracy in discriminating LTBI from active tuberculosis can be improved by parallel assessment of the secreting profile of T-cells for other cytokines, such as IL-2 and TNF-α." (PMID 28961208, 2017). "The number of IL-2- IFN- γ+ producing cells was higher in patients with tuberculosis compared with past tuberculosis (CFP-10-induced p = 0.0068) or individuals with LTBI (ESAT-6-induced p = 0.0136)." (PMID 25785445, 2015). "IL-2 was described previously as a marker of ‘polyfunctional’ T-cells which are crucial for protection against tuberculosis." (PMID 25742660, 2015). "In conclusion, antigen-specific IL-2- IFN-γ+ secreting T-cells are elevated in active tuberculosis in comparison to past tuberculosis and LTBI and can be easily identified by FluoroSpot." (PMID 25785445, 2015). "Recent publications suggest that the accuracy in discriminating LTBI from active tuberculosis can be improved by parallel assessment of the secreting profile of T-cells for other cytokines, such as interleukin (IL)-2 and/or tumor necrosis factor (TNF)-α." (PMID 25785445, 2015). "The FluoroSpot detected significantly elevated ESAT-6-specific IL-2- IFN-γ+ T-cells in tuberculosis in comparison to past tuberculosis and LTBI." (PMID 25785445, 2015). "Different studies have shown that both tuberculosis and HIV infection can inhibit T cell effector functions, such as production of IFN-γ and interleukin-2, and co-infection is associated with more profound suppression of type-1 cytokine responses." (PMID 24592945, 2014).
tuberculosis (continued). "All M. tuberculosis-specific CD4+ subsets, with the exception of IL-2-only cells, switched from central to effector memory phenotype in active tuberculosis vs latent tuberculosis infection, accompanied by a reduction in IL-7 receptor α (CD127) expression." (PMID 23966657, 2013). "Clearly, further studies are needed to evaluate the role of the TNFα/IL-2 expressing cells in the maintenance of long-term anti-tuberculosis cellular responses induced by BCG-containing vaccines." (PMID 22442674, 2012). "During active tuberculosis, suppression of Mtb. specific T cell response is evidenced by decreased production of the cytokines such as IL-2 and interferon IFN-γ with simultaneous over production of suppressive cytokines such as IL-10 and TGF-β." (PMID 23028594, 2012). "Recently, a shift in the IFN-γ and IL-2 cytokine profile from a codominance of IFN-γ-only and IFN-γ/IL-2-secreting T cells and the appearance of IL-2-only secreting T-cells during and after treatment of tuberculosis has been demonstrated." (PMID 20652022, 2010). "Interferon-γ (IFN-γ) ELISpot was performed using PBMC from 40 persons with active or latent tuberculosis, and IL-2 ELISpot on 13 and 14 persons in each category." (PMID 21203487, 2010). "Among the six contacts tested positive on IL-2 ELISpot was a 51 year-old female teacher who reported intensive tuberculosis contact more than 20 years ago." (PMID 20652022, 2010). "The LTBI signature differed from active tuberculosis, with higher proportions of IL-2-only and IFN-γ/IL-2-secreting T-cells and lower proportions of IFN-γ-only-secreting T-cells." (PMID 21179481, 2010). "When we analyzed human immune responses to this protein in tuberculosis infected people our experiments showed it was particularly well recognized by cells that produce a chemical messenger (cytokine) called interleukin-2." (PMID 21203487, 2010). "Consequently, IL-2 emerges as a promising candidate for incorporation as an adjuvant in tuberculosis vaccine formulations." (PMID 38793728, 2024). "In addition, previous reports revealed that the expression of Th1 cytokines (IFN-γ and IL-2) decreased in tuberculosis patients." (PMID 36733703, 2023). "Similarly, the concentration of IL-6 was significantly increased and IL-4 decreased in SA, and the concentrations of INF-γ, IL-2, IL-4 and IL-10 were significantly lower in tuberculosis, compared to those in healthy subjects." (PMID 36982159, 2023). "Among the various cytokines, pro-inflammatory cytokines (TNF-α, IL-6, and IL-1β), and Th1 cytokines (IL-12, IFN-γ, and IL-2) are known to confer significant protection against tuberculosis, while anti-inflammatory cytokines (IL-10 and TGF-β) and type-I interferons (IFN-β) confer susceptibility." (PMID 35832818, 2022). "In addition, rs414171-T allele that was associated with susceptibility to bacteremia, tuberculosis and malaria has been shown to reduce the promoter activity of CISH and its expression in human PBMCs after stimulation by IL-2." (PMID 34072601, 2021). "Moreover, NAC modulated immunity against tuberculosis where it increased interleukin-2 (IL-2), IL-12, and interferon gamma (INF-γ) production and these cytokines are important for suppressing mycobacterial proliferation." (PMID 32411461, 2020). "Similarly, a previous study also reported that IL10 and IL2 accurately identified active tuberculosis from LTBI cases." (PMID 32962082, 2020). "Studies exploring recombinant human interleukin 2 (rhuIL-2) as an adjunctive immunotherapeutic agent to treat tuberculosis (TB) have shown variable results; however, the true therapeutic efficacy of rhuIL-2 administration in TB patients has not been determined." (PMID 30024982, 2018). "Differences found in the IL-2 levels between AS-Li and AS-Ld might be related with a remote or recent infection, respectively, as described in tuberculosis." (PMID 28620584, 2017).